FAM163A (family with sequence similarity 163 member A)
Synonyms: C1orf76; NDSP; MGC16664
Tractability: Antibody: UniProt predicts a signal peptide or a membrane-spanning region.
Gene: Protein-coding gene on chromosome 1 (179,743,291 to 179,817,055, forward strand). Ensembl gene ENSG00000143340.
Subcellular location: Membrane
Gene Ontology:
Molecular function: protein binding
Cellular component: membrane
Genetic constraint (gnomAD): Loss-of-function variants: 7 observed, 10.92 expected, observed/expected ratio (o/e) 0.64, 90% interval 0.36 to 1.2. The upper end of that interval is the gene's LOEUF score, 1.2, which puts it in group 5 of 6, group 1 being the genes least tolerant of losing a copy. Missense variants: 202 observed, 221.09 expected, observed/expected ratio (o/e) 0.91, 90% interval 0.81 to 1.03. Synonymous variants: 101 observed, 94.65 expected, observed/expected ratio (o/e) 1.07, 90% interval 0.91 to 1.26.
Homologues: Orthologues: chimpanzee FAM163A (99% identical), macaque FAM163A (98% identical), pig FAM163A (92% identical), guinea pig FAM163A (90% identical), rat Fam163a (89% identical), dog FAM163A (88% identical), rabbit FAM163A (87% identical), mouse Fam163a (86% identical), zebrafish fam163aa (50% identical), tropical clawed frog FAM163A (43% identical), zebrafish fam163ab (40% identical).
Diseases named in the same sentence as FAM163A in open-access papers:
FAM163A is named in the same sentence as 9 diseases in open-access papers, as found by Europe PMC text mining. Sharing a sentence is not in itself a finding about the gene and the disease. The quoted sentences say what the papers report.
neuroblastoma (2 papers, 2019 to 2022). Neuroblastoma (NB) is the most common solid, extracranial childhood tumor. "FAM163A, located on chromosome 1q25.2 and encoding a 167-amino acid protein, is also recognized as neuroblastoma-derived secretory protein (NDSP) or C1ORF76." (PMID 35391800, 2022).
bipolar disorder (1 paper, 2016). A disorder of the brain that causes unusual shifts in mood, energy, activity levels and the ability to carry out day-to-day tasks. "Few changes were identified following this treatment, although four proteins—FAM163A, RIN1, mTOR and MCCC1—shown to be dysregulated in bipolar disorder were dysregulated in the same direction by haloperidol treatment, suggesting that these effects may have been drug treatment-related." (PMID 27898073, 2016).
diabetes (1 paper, 2023). "Of these DMPs, 17 (94.4%) showed hypermethylation in newborns whose mothers had diabetes in pregnancy, whereas only 1 DMP (cg21363811) located within the CpG island of the FAM163A gene showed hypomethylation." (PMID 37029435, 2023).
pituitary tumor (1 paper, 2019). A benign or malignant neoplasm affecting the pituitary gland. "In addition, we looked at genes that were not previously investigated in pituitary tumors, FAM163A, HIF3A, and PRSS8, which were hypermethylated in NFPAs." (PMID 31731486, 2019).
cancer (2 papers, 2022 to 2023). A tumor composed of atypical neoplastic, often pleomorphic cells that invade other tissues. "The gene with the second highest MS was FAM163B, which has not yet been elucidated, but its paralog FAM163A (also known as NDSP) is associated with an increased risk for the development of cancer metastasis in bone marrow." (PMID 37761960, 2023). "According to the Cancer Cell Line Encyclopedia (CCLE), with high mRNA levels in NB, FAM163A has a notable cancer type specificity." (PMID 35303940, 2022).
FAM163A also shares sentences with these, for which no sentence is quoted: autoimmune disease (1 paper); lung carcinoma (1); squamous cell lung carcinoma (1); tumours (1).